COCH (cochlin)
Description:
Plays a role in the control of cell shape and motility in the trabecular meshwork.
Synonyms: COCH5B2; COCH-5B2; DFNA9; DFNB110; formerly DFNA31
Tractability: Antibody: UniProt places it where antibodies can reach, with high confidence; its Gene Ontology location is reachable by antibodies, with high confidence; UniProt predicts a signal peptide or a membrane-spanning region.
Gene: Protein-coding gene on chromosome 14 (30,874,438 to 30,895,065, forward strand). Ensembl gene ENSG00000100473.
Subcellular location: Secreted, extracellular space, extracellular matrix
Subcellular location (Human Protein Atlas): Vesicles; Predicted to be secreted
Gene Ontology:
Molecular function: collagen binding; protein binding
Biological process: regulation of cell shape; sensory perception of sound
Cellular component: extracellular matrix; non-collagenous component of interstitial matrix
Genetic constraint (gnomAD): Loss-of-function variants: 37 observed, 54.35 expected, observed/expected ratio (o/e) 0.68, 90% interval 0.52 to 0.9. The upper end of that interval is the gene's LOEUF score, 0.9, which puts it in group 3 of 6, group 1 being the genes least tolerant of losing a copy. Missense variants: 594 observed, 692.45 expected, observed/expected ratio (o/e) 0.86, 90% interval 0.8 to 0.92. Synonymous variants: 251 observed, 244.4 expected, observed/expected ratio (o/e) 1.03, 90% interval 0.93 to 1.14.
Gene-disease validity (ClinGen):
ClinGen rates the evidence that COCH causes each of these diseases.
nonsyndromic genetic hearing loss (autosomal dominant): Definitive. A disease characterized by hearing loss that is not part of a larger syndrome.
Homologues: Orthologues: chimpanzee COCH (100% identical), macaque COCH (99% identical), pig COCH (96% identical), dog COCH (96% identical), guinea pig COCH (95% identical), rabbit COCH (95% identical), mouse Coch (94% identical), rat Coch (92% identical), tropical clawed frog coch (66% identical), zebrafish coch (59% identical). Paralogues in human: COL12A1 (28% identical), COL14A1 (24% identical), COL6A3 (24% identical), MATN4 (22% identical), MATN1 (22% identical), MATN2 (22% identical), COL6A6 (21% identical), VWA2 (19% identical), COL6A5 (18% identical), VIT (15% identical), MATN3 (12% identical), VWA1 (9% identical).
Diseases named in the same sentence as COCH in open-access papers:
COCH is named in the same sentence as 61 diseases in open-access papers, as found by Europe PMC text mining. Sharing a sentence is not in itself a finding about the gene and the disease. The quoted sentences say what the papers report.
hearing loss (35 papers, 2012 to 2025). "HL associated with the MYO6, TECTA, and COCH genes was identified in patients with mild hearing loss." (PMID 38790200, 2024). "Cochlin has been well mapped in the inner ear36–38, and cochlin mutations are a known genetic cause of adult late-onset sensorineural hearing loss." (PMID 38898156, 2024). "In conclusion, our findings enriched the phenotypic and variant spectrum of DFNA9 in Chinese people and implied the importance of the diagnosis of the COCH gene in patients with late-onset hereditary hearing loss." (PMID 38255649, 2023). "Late-onset non-syndromic autosomal dominant hearing loss 9 (DFNA9) is a hearing impairment caused by mutations in the coagulation factor C homology gene (COCH)." (PMID 35901072, 2022). "In general, variants affecting the LCCL domain of cochlin lead to more progression of hearing loss when compared to variants affecting the other domains." (PMID 35204720, 2022). "Variants affecting the LCCL domain of cochlin generally lead to more progression of hearing loss when compared to variants affecting the other domains." (PMID 35204720, 2022). "In contrast, Coch−/− mice have higher ABR and DPOAE thresholds compared to Coch+/+ mice at the age of one year while recessive COCH patients suffer from congenital hearing loss." (PMID 34768980, 2021). "The c.151C>T (p.Pro51Ser) founder mutation, affecting the LCCL domain, appears to be the most prevalent mutation in COCH, as it underlies hearing loss in >1,000 Dutch and Belgian individuals." (PMID 33815940, 2021). "The c.151C>T founder mutation in COCH is a frequent cause of late-onset, dominantly inherited hearing impairment and vestibular dysfunction (DFNA9) in the Dutch/Belgian population." (PMID 33815940, 2021). "The c.151C>T founder mutation in COCH is a frequent cause of late-onset, dominantly inherited hearing impairment and vestibular dysfunction (DFNA9)." (PMID 33815940, 2021). "The c.151C>T founder mutation in COCH is estimated to be one of the most prevalent causes of dominantly inherited, adult-onset hearing loss and vestibular dysfunction in Northwest Europe, affecting >1,000 individuals in the Dutch/Belgian population." (PMID 33815940, 2021). "In our hearing loss family #32 with the same mutation of c.889G>A (p.C162Y) in COCH gene, the affected members presented with early-onset hearing loss in the 2nd decade of life." (PMID 28099493, 2017). "We therefore suggest that the disrupted cleavage of the LCCL domain fragment is likely to cause vestibular dysfunction, and aggregation of mutant cochlin caused by mutations in the vWFA domain is responsible for early-onset hearing loss." (PMID 28099493, 2017). "Significant aggregation of cochlin is more likely to cause cochlear dysfunctions such as early-onset hearing loss and sudden deafness." (PMID 28099493, 2017). "Although COCH mutations have only been associated with DFNA9 so far, a gene linked to hearing loss disorder, Cochlin deposits were detected in glaucomatous TM as well as DBA/2J glaucomatous mouse TM but not in normal controls." (PMID 24063017, 2013). "In this context it is worthwhile to mention that deposition of cochlin, a protein implicated in non-syndromic hearing loss, was found in glaucomatous TM cells." (PMID 23940637, 2013). "A total of 11 proteins, including cochlin, myosin VI, and myosin IX, were identified that when defective are associated with hearing impairment or loss." (PMID 22942697, 2012). "Additionally, a family with a mutation in COCH, a gene related to the hearing loss disorder DFNA9, was found to have an MD-like phenotype with asymmetric SNHL, unilateral aural symptoms, and episodic vertigo." (PMID 33613440, 2021). "However, hearing loss can explain the association between tinnitus and the COCH variant, judging from the fact that the tinnitus of patients with COCH variants is secondary from hearing loss." (PMID 32747715, 2020).
hearing loss (continued). "As a consequence, hearing loss in that population could be due to other genes, as we started to point out for two of our patients, with a pathogenic variant in COCH and a suspected one in MYH14." (PMID 31393079, 2019). "Moreover, no pathogenic mutation was found in the ACTG1, KCNQ4, GJB3, or COCH genes in patients with late onset hearing loss and autosomal dominant pedigrees or in patients with sporadic hearing loss." (PMID 30344259, 2018). "So, the failure of mutant cochlin transport, which impairs cochlin secretion, induces the formation and retention of dimers and large multimeric intracellular aggregates, which correlates with an earlier onset and progression of hearing loss in DFNA9." (PMID 27083884, 2016). "Several dominantly inherited types of hearing loss present in adulthood, including DFNA9, which is caused by COCH missense variants." (PMID 41463124, 2025). "Systematic genotype–phenotype correlations in DFNA9 highlight that specific COCH variants, particularly those affecting the LCCL domain, are associated with faster hearing loss progression." (PMID 41463124, 2025). "In DFNA9, a form of dominantly inherited HL, the c.151C>T founder mutation in COCH has been shown to cause progressive hearing impairment in the Belgian–Dutch population." (PMID 38137568, 2023). "Further, they provide a viable platform for modelling vestibular dysfunction, an often overlooked comorbidity that frequently occurs with inherited hearing loss, for example in association with mutations in CLIC5, COCH and ESPN." (PMID 36331565, 2022). "COCH Cys542Phe and MYO6 His246Arg are known pathogenic variants, and consistent with this, we observe almost all carriers presenting hearing loss." (PMID 35661827, 2022). "The interest in cochlin deposition was based on the work of Robertson (2001, 2006) who demonstrated increased eosinophilic deposits of cochlin in the ampullary stroma of patients with hereditary DFNA9-associated hearing loss and vestibular dysfunction." (PMID 39725698, 2024). "Although Cochlin has been considered another promising candidate for evaluating inner-ear impairment in autoimmune inner-ear diseases, IgG antibodies to human Cochlin play a lesser role in hearing impairment in patients with RA." (PMID 39769062, 2024). "While researchers have suggested potential roles for plasma matrix metalloproteinases (MMPs) and cochlin in detecting hearing impairment linked to RA, conclusive results have not yet been achieved." (PMID 39769062, 2024). "COCH has also been identified as the causative gene for DFNA9, a hereditary hearing loss." (PMID 37479821, 2023). "A possible explanation for the high occurrence of hearing loss in our BVP cohort, might be the high prevalence of genetic causes of BVP, i.e., COCH mutations." (PMID 31105513, 2019). "Cochlin overexpression has been linked to nerve damage; suggesting a mechanism by which the COCH upregulation observed in our data may correlate with nerve damage related to hearing loss." (PMID 38440980, 2024). "Mutations in the COCH gene lead to autosomal dominant nonsyndromic sensorineural deafness 9 (DFNA9), which has been clinically characterized by progressive late-onset hearing loss with or without vestibular dysfunction." (PMID 25388789, 2014). "Our result enriched the spectrum of DFNA9-linked pathological COCH variants and suggested that variants, causative of cochlin multimerization, could be related to DFNA9 with sensorineural hearing loss rather than serious vestibular symptoms." (PMID 38255649, 2023). "However, recent studies detected COCH variants at the protein’s C-terminus that co-segregated with DFNA9 hearing impairment in pedigrees, suggesting that proper function of the non-domain region of cochlin was also required for normal hearing." (PMID 38255649, 2023).
deafness (18 papers, 2011 to 2025). An inherited or acquired condition characterized by the complete loss of the ability to hear from one or both ears. "Nineteen deafness genes were linked with vestibular symptoms; the most frequent genes in autosomal dominant and recessive individuals were COCH and SLC26A4, respectively." (PMID 38610765, 2024). "The other tested genes, including the deafness gene COCH, in which mutation recapitulates deafness in mice, were expressed in a similar manner in both species." (PMID 26915689, 2016). "Mutations in nine deafness genes (COCH, KCNQ4, MYO7A, TECTA, CRYM, POU3F4, EYA1, mitochondrial tRNA(Lys) m.8296A>G, mitochondrial tRNA(Ser) m.7445A>G) were not identified in any patients." (PMID 22384008, 2012). "Several of the genes identified in our analyses were previously studied in the inner ear and a few (e.g., crystallin and cochlin) have been shown to cause deafness." (PMID 21483685, 2011). "Gradual structural changes in GAGs could explain early onset deafness in DFNA9 patients with various point mutations in the COCH gene." (PMID 35901072, 2022). "The del(GJB6-D13S1830), SERPINB6, TMIE, COCH, ESPN, ACTG1, GJB3, and KCNQ4 mutations were infrequently associated with deafness in the Moravian-Silesian population." (PMID 30344259, 2018). "Among a number of nonsyndromic deafness genes, variants in SLC26A4, COCH, MYO7A, GRHL2, and CLIC5 as well as POU4F3 are known to cause vestibular symptoms and/or dysfunction." (PMID 28545070, 2017). "On the other hand, the expression pattern of COCH, which has a mouse model that recapitulates the deafness phenotype of patients, was conserved between mouse, human, and marmoset." (PMID 26915689, 2016). "In clinical otology and audiology, we may occasionally see a patient with a very “focal” lesion accounting for their hearing loss, for example, the monogenic COCH mutation of DFNA9 deafness or the many otoferlin mutations of DFNB9 deafness." (PMID 37425006, 2023). "The most frequent causative deafness gene was TMC1 (DFNA36) (3 cases), followed by the next tier of genes (2 cases each) (CDH23, COCH, SLC26A4, TMPRSS3, ATP1A3), and the genes that were detected only once (ACTG1, GJB2, ILDR1, MYO7A, MYO15A, NF2, NLRP3 and SERPNB6)." (PMID 32238869, 2020). "This hypothesis is supported by our present data, especially by our transcriptome analysis as inherited deafness genes (such as COCH (coding for cochlin), TIMM8B, PRPS1 and tRNA synthetase) are downregulated in AK2-deficient cells." (PMID 26270350, 2015). "Of them, three were novel missense mutations (p.G38D in COCH, p.E316K in ACTG1, and p.P164R in POU4F3), one was a novel in-frame indel mutation (c.2036-2038delAGG in WFS1), and two were known deafness-causing mutations that have been previously reported (p.R653C in WFS1 and p.D572N in TMC1)." (PMID 25388789, 2014). "The present study focuses on DeaFNess Autosomal 9 (DFNA9), an autosomal dominantly inherited inner ear disorder (ORPHA: 90635), caused by pathogenic variants in the Coagulation Factor C Homology (COCH) gene." (PMID 38167558, 2024). "Successful humanization of mouse models for deafness genes, like MYO6 and COCH, has yielded critical insights into the molecular mechanisms of hearing diseases." (PMID 40089864, 2025). "We also examined the expression profiles of COCH (DFNA9) and CONNEXIN26 (CX26, DFNA3A, DFNB1A), which have mouse models that recapitulate the deafness phenotype." (PMID 26915689, 2016).
Menière’s disease (9 papers, 2020 to 2023). "Some DFNA9 patients with COCH mutations located in the LCCL domain share manifestations assembling Meniere’s disease." (PMID 38255649, 2023). "Overexpression of cochlin in the early stage of Meniere’s disease may be one of the causes of intractable Meniere’s disease." (PMID 35958995, 2022). "Besides DFNA9, cochlin is involved in several other disorders such as Menière's disease and immune-mediated inner ear disease (IMED)." (PMID 33193034, 2020). "There are data suggesting that Cochlin is overexpressed in the vestibular endorgans of subjects with persistent Ménière’s disease and in autoimmune inner ear disease, which may contribute to the dysregulation of the environmental balance within the inner ear in Ménière’s disease." (PMID 35958995, 2022).
glaucoma (6 papers, 2013 to 2023). Increased pressure in the eyeball due to obstruction of the outflow of aqueous humor. "A similar phenomenon has been observed in the eye, where upregulation of cochlin results in a higher intraocular pressure (IOP) causing glaucoma." (PMID 34768980, 2021). "Proteomic studies and expression analyses of the trabecular meshwork (TM) from patients with POAG and age-matched controls implicated Cochlin as a potential contributing factor to glaucoma pathogenesis." (PMID 24063017, 2013). "However, other glaucoma-associated factors such as sFRP1,52 gremlin, serum amyloid A,52 sCD44,53 and cochlin, also may be epigenetically regulated to elevate IOP." (PMID 27403998, 2016). "However, considering the minor contribution of each of the POAG loci identified so far to glaucoma pathogenesis, a screening effort in a much larger cohort from different regions of India could truly reflect the state of association of COCH and TNFA with POAG." (PMID 24063017, 2013). "COCH is also expressed by the endothelial cells within the trabecular meshwork of subjects with primary open-angle glaucoma (POAG), another common age-related degenerative disorder." (PMID 32463444, 2020). "The excessive deposition of cochlin and its interaction with mucopolysaccharide in the trabecular meshwork ECM contribute to increased resistance of aqueous humor outflow in both glaucoma patients and a glaucomatous rodent model." (PMID 37644183, 2023). "Our data, for the first time, suggests the involvement of an interaction of cochlin and TREK-1 in glaucoma and renders this interaction a target for therapy." (PMID 28352076, 2017). "With this background, we investigated the involvement of COCH and TNFA in glaucoma pathogenesis in a cohort of east Indian POAG patients." (PMID 24063017, 2013).
autoimmune inner ear disease (3 papers, 2020 to 2024). A syndrome characterized by rapidly progressive sensorineural hearing loss (SNHL), that is often bilateral, and is potentially reversible. "Moreover, cochlin was found to be overexpressed in MD and autoimmune inner ear disease." (PMID 33383894, 2020).
sensorineural hearing loss (3 papers, 2016 to 2023). "Previous research has demonstrated that mutations in the COCH gene cause DFNA9, an autosomal dominant disorder that causes progressive sensorineural hearing loss associated with vestibular dysfunction." (PMID 33193034, 2020).
autosomal dominant nonsyndromic hearing loss (2 papers, 2024 to 2025). Autosomal dominant form of nonsyndromic deafness. "Mutations in COCH were associated with autosomal dominant nonsyndromic hearing loss and vestibular dysfunction, possibly by altering the interaction between cochlin and type II collagen in the inner ear." (PMID 39452111, 2024).
clear cell renal cell carcinoma (2 papers, 2020). "Up-expression of COCH was directly related to the stage progression of clear cell renal cell carcinoma (ccRCC)." (PMID 33281116, 2020).
inner ear disease (2 papers, 2024 to 2025). "Recent studies have shown that cochlin is also expressed by pericytes of the inner ear and may regulate their adhesion and migration, suggesting that COCH mutations may impact pericyte function and contribute to the pathogenesis of inner ear disorders." (PMID 39452111, 2024). "Fundamental research on cochlin has highlighted its role as a potential autoantigen in immune-mediated inner ear disease, a finding supported by a recent systematic review." (PMID 41306961, 2025).
lymph node metastases (2 papers, 2021 to 2024). "As a DNA methylation marker, COCH has shown effectiveness in identifying occult lymph node metastases in non-small cell lung cancer." (PMID 38327746, 2024). "Methylation levels of COCH are elevated in the plasma of NSCLC patients with lymph node metastasis." (PMID 33869220, 2021).